CAV1 (caveolin 1)
Diseases named in the same sentence as CAV1 in open-access papers (continued):
Sharing a sentence is not in itself a finding about the gene and the disease.
melanoma (continued). "Thus, also for human melanoma cells introduced directly into the blood stream, augmented expression of CAV1 expression favoured metastasis, in this case not only to the lung but also to the liver." (PMID 24500501, 2014). "We then sought to develop a mouse model to evaluate how CAV1 presence in subcutaneous melanoma tumours might impact on their potential to regenerate tumours at the initial site as well as to metastasize to the lung." (PMID 24500501, 2014). "For melanomas, relatively little is known about the role of CAV1." (PMID 24500501, 2014). "Expression of ANXA1, CAV-1 and EphA2 were analysed in 124 melanoma samples by immunohistochemistry." (PMID 25594008, 2014). "Therefore, the presence of CAV1 in melanoma cells that were introduced directly into the blood stream elevated the metastatic potential of these cells." (PMID 24500501, 2014). "Co-expression of SRC, ANXA1, CAV-1 and EphA2 was detected in 35/113 (31 %) of melanoma samples." (PMID 25594008, 2014). "In addition, we developed a new experimental protocol similar to that used by surgeons in patients and found again that CAV1 expression in mouse and human melanomas favours metastatic dissemination after tumour surgery." (PMID 24500501, 2014). "However, the characterization in vitro of both B16F10 and A375 melanomas shows that CAV1 expression enhances migration and Rac1 activation 4,19 as well as invasion in a matrigel assay (data not shown)." (PMID 24500501, 2014). "Interestingly, elevated protein expression of ANXA1, CAV-1 and EphA2, determined by semi-quantitative immuno-blotting, correlated with dasatinib sensitivity in the melanoma cell lines." (PMID 25594008, 2014). "Thus, in this animal model for melanoma surgery, we found that CAV1 expression in B16F10 cells generated less tumour mass at the primary site and yet enhanced metastasis to the lung." (PMID 24500501, 2014). "Moreover, a recent report suggests that caveolin-1 expression in B16-F10 mouse melanoma cells decreases cell migration and experimental metastasis." (PMID 22505999, 2012). "Since two metastatic (breast and melanoma) cell types from different species (human and mouse) were characterized in a variety of settings, our observations have broad implications for the role of caveolin-1 in rapidly migrating cells and cancer." (PMID 22505999, 2012). "Moreover, we recently showed that Cav1 is highly expressed on vesicular structures of endolysosomal compartment in human melanoma cells." (PMID 19381331, 2009). "Interestingly, paired T-test showed that plasma levels of Cav1+ exosomes were significantly higher than levels of CD63+ exosomes in melanoma patients (P = 0.004)." (PMID 19381331, 2009). "Therefore, we investigated the presence of Cav1 on exosomes obtained from plasma of SCID mice engrafted with melanoma tumors." (PMID 19381331, 2009). "Similarly, Díaz-Valdivia reported that phosphorylated Cav-1 facilitates the metabolic shift by enhancing glycolysis while inhibiting mitochondrial respiration, leading to increased reactive oxygen species (ROS) levels, which further drive Cav-1-induced cell migration and invasion in melanoma cells." (PMID 40243482, 2025). "Finally, our results show that PGE2 exposure disrupts the tumor and metastasis suppressor effects of the CAV1/E-cad complex to favor CAV1 phosphorylation on tyrosine-14, resulting in enhanced migration, invasion, and metastasis of melanoma cells, as indicated in our working model." (PMID 38069269, 2023). "Thus, it was interesting to determine whether something similar could happen in melanoma cells, where the CAV1/E-cad complex has a strong tumor suppressor effect." (PMID 38069269, 2023). "Moreover, an increase in circulating exosomes expressing Cav-1 has been identified in the serum of melanoma patients, suggesting that Cav-1 may represent a prognostic biomarker." (PMID 35334544, 2022).
melanoma (continued). "To ensure that the data obtained using tumor-derived tissue reflected a response elicited predominantly in tumor cells rather than the stromal compartment, we next asked whether suppression of the UPR by CAV1 expression was maintained in melanoma cells isolated from tumors (ex-tumor)." (PMID 32811828, 2020). "Interestingly, the microRNA-203a (miR-203a) downregulates Cav1 expression in melanoma cells." (PMID 32532976, 2020). "Also, the phosphorylation of CAV1 is required for melanoma metastasis." (PMID 32458269, 2020). "Furthermore, others also detected CAV1 in the CM of human melanoma cells." (PMID 32458269, 2020). "Furthermore, exosomes secreted by melanoma cells in an acidic condition could deliver caveolin-1 that is a protein involved in melanoma progression." (PMID 31438991, 2019). "CAV1-containing exosomes and melanoma cells lacking CAV1 were used to test whether low pH conditions, a hallmark of tumor malignancy, increase the intercellular incorporation of tumor-associated molecules through exosomes." (PMID 31362353, 2019). "Therefore, resistin-mediated impairment of DTIC treatment in melanoma cells could be due to collective involvement of Cav-1 and P-gp, both being integral component of plasma membrane of cancer cells." (PMID 29568521, 2018). "Thus, a possible alternative interpretation is that our observations reflect a system in which intrinsic CAV1 levels in tumour cells may be transferred to stromal cell populations and condition a niche for metastatic melanoma cells." (PMID 24500501, 2014). "Thus, the role of CAV1 in melanoma and particularly the possible consequences of CAV1 expression for patient survival postintervention remain unclear." (PMID 24500501, 2014). "Interestingly, Cav1 has been reported to promote growth and invasion of melanoma cells." (PMID 25538140, 2014). "Thus, although CAV1 shows characteristics typical of a tumour suppressor in subcutaneous tumour formation assays using human melanomas, these beneficial traits appear to be lost once cells reach the blood stream, as may occur unintentionally following surgery." (PMID 24500501, 2014). "In conclusion, our results suggest that IHC staining for ANXA1, CAV-1 and/or EphA2 may form the basis of a biomarker panel to select melanoma patients for a biomarker-driven clinical trial of dasatinib, to better define the potential clinical benefit of dasatinib in melanoma treatment." (PMID 25594008, 2014). "Thus, we reasoned that it would be most appropriate to evaluate additionally the consequences of CAV1 expression in melanoma in a clinically more relevant setting for metastasis, akin to the situation in human patients, where subcutaneous tumours are surgically removed." (PMID 24500501, 2014). "In contrast the ability of melanoma cells to form lung metastases seems to be significantly reduced in Cav1KO mice: this behaviour has been linked to the inability of melanoma cells to adhere to and to transmigrate through a monolayer of endothelial cells lacking Cav1." (PMID 23521716, 2013). "In melanoma, ATP1A1 forms a complex with Cav-1 to activate Src/AKT signaling, promoting therapeutic resistance and T-cell suppression." (PMID 40821775, 2025). "Caveolin-1, which is closely related to FAM198A and retained in the ER, regulates melanoma by modulating the secretory pathway in a manner depending on the inhibition of the UPR." (PMID 36825005, 2023). "In summary, co-overexpression of CAV1 with E-cad suppressed CAV1-enhanced migration and invasion of B16F10 melanoma cells, and exposure of these cells to PGE2 abolished the ability of E-cad to restrict the pro-metastatic function of CAV1." (PMID 38069269, 2023). "We found that Cav1 and E-cadherin (CDH1) were upregulated in de-differentiated or differentiated melanomas, respectively." (PMID 36271142, 2022).
melanoma (continued). "For that purpose, we used B16F10 mouse melanoma and HT29(US) colon cancer cells transfected with the IPTG-inducible plasmid pLacIOP (Mock) or pLacIOP-caveolin-1 (CAV1) vectors." (PMID 35740528, 2022). "Meanwhile, an in-house study of melanoma reported that there was a higher level of CD63+ exosomes in cancer plasma, which was correlative with the level of caveolin-1, a component of caveolae." (PMID 35757760, 2022). "Cav-1, stabilized by FASN by palmitoylation, is involved in drug resistance and therefore constitutes a tumor-promoting factor in melanoma." (PMID 33430277, 2021). "We show here for metastatic breast, colon, and melanoma cells that the overexpression of PTPN14 reduces CAV1 pY14, as well as CAV1-induced migration and invasion in vitro, and the metastasis promoting role of CAV1 in vivo." (PMID 32152405, 2020). "EVs from melanoma patients consist of the melanoma-specific protein, very late antigen, tyrosinase-related protein-2, MET, caveolin-1, and Hsp70 as compared to the healthy control, rendering them a potential biomarker in melanoma." (PMID 33260606, 2020). "Upon leptin and resistin treatment using A375 melanoma cell line, fatty acid synthase (FASN) and caveolin 1 (Cav-1), respectively, were found increased." (PMID 32509589, 2020). "By using an immunocapture-based assay, it was shown that patients with advanced melanoma patients (stage III and IV) had higher plasmatic exosomes levels as compared to healthy donors, with the best results with exosomes expressing caveolin-1." (PMID 32916840, 2020). "Specifically, CAV1 was shown to activate a novel CAV1/Rab5/Rac-1 signaling axis that requires phosphorylation of CAV1 on tyrosine-14, which is also essential in B16F10 melanomas to promote lung metastasis." (PMID 31484460, 2019). "Previously, we have reported that obesity impairs efficacy of DTIC in melanoma, which is mediated by FASN and Cav-1." (PMID 29568521, 2018). "Alternatively, CAV1 promotes migration of metastatic breast cancer (MDA-MB-231), colon cancer (HT29(US)) and melanoma (B16F10, A375M) cells via activation of the Rab5-Rac1 signaling axis." (PMID 29340103, 2017). "This suggests that altered levels of adipocyte-secreted factors are involved in modulating FASN, Cav-1, and P-gp levels which, in turn, influence the outcome of DTIC therapy in melanoma cells." (PMID 27980732, 2016). "Previous data obtained in B16F10 melanoma and MDA-MB-231 breast cell lines using PP2, a selective pharmacological inhibitor of the Src family kinases, prevented CAV1-enhanced wound closure." (PMID 27259249, 2016). "Specific cell interactions with fibronectin and laminin are shown to stimulate phosphorylation of CAV1 on Y14 and thereby enhance velocity, persistency and directionality of B16F10 melanoma migration." (PMID 27259249, 2016). "Phosphorylation of CAV1 on Y14 stimulated by binding to fibronectin and laminin, correlated with enhanced migration of B16F10 melanoma cells on these surfaces." (PMID 27259249, 2016). "In the present study, we used the B16F10 murine melanoma model and determined the role of individual ECM components and Y14 phosphorylation of CAV1 in cell adhesion, spreading and migration." (PMID 27259249, 2016). "Melanoma cells grown under these conditions develop chemo-resistant phenotype, characterized by increased expression of FASN, Cav-1, and P-gp." (PMID 27980732, 2016). "We showed that in human melanoma NRASQ61K PTEN-null cells, p16INK4A is repressed through CAV1/β-catenin; this interaction is ablated on PTEN re-expression." (PMID 26307673, 2015). "Published data suggests that CAV1 can be an important regulator of the expression and activity of MMPs, including CAV1 unregulated MMP-2 and 9 in melanoma cells." (PMID 25180681, 2014).
melanoma (continued). "Given the importance of surgical procedures as an initial line of defence to eradicate melanomas, we used human A375 cells in immunodeficient B6Rag1−/− mice and mouse B16F10 cells in syngenic C57BL6 mice to evaluate how CAV1 affected surgery outcome." (PMID 24500501, 2014). "If SRC kinase staining is added to the panel, 19/113 (17 %) of the melanomas express detectable levels of SRC kinase and have moderate/strong expression of ANXA1, CAV-1 and EphA2." (PMID 25594008, 2014). "Pearson correlation coefficient analysis was used to examine the relationship between mRNA and protein expression of ANXA1, CAV-1, CAV-2, EphA2, IGFBP2 and PTRF in the panel of melanoma cell lines." (PMID 25594008, 2014). "Moderate/strong expression of ANXA1, CAV-1 and EphA2 with co-expression of SRC kinase was found in 17 % of melanoma samples." (PMID 25594008, 2014). "Seventeen percent (19/112) of melanoma samples were positive for SRC kinase expression, combined with high expression of ANXA1, CAV-1 and EphA2." (PMID 25594008, 2014). "Our finding that FASN and Cav-1 interact is an indicative of similarities in the modulation of FASN by Cav-1 and vice versa between HCC cells and melanoma." (PMID 23613870, 2013). "Cav1 was detected in exosomes preparations derived from plasma of SCID mice engrafted with melanoma tumors by WB, FACS and ELISA while Cav1 was undetectable in plasma-derived exosomes from control animals." (PMID 19381331, 2009). "Since CAV1 mRNA and protein overexpression can induce EMT marker overexpression in various cancer cell lines, CAV1, that participates to caveolar endocytosis, could be intermediate between PROM2 and EMT markers in our in vitro and in vivo melanoma models." (PMID 38515278, 2024). "CAV1 can act as a tumor suppressor or tumor promoter depending on the cell type, although its role in melanoma has not yet been elucidated." (PMID 36431795, 2022). "Here, we characterized by mass spectrometry the protein composition of CAV1 immunoprecipitates from B16F10 murine melanoma cells expressing or not E-cadherin." (PMID 32152405, 2020). "We previously established an in vivo model using B16F10 melanoma cells in non-immunosuppressed syngeneic C57BL/6 mice to demonstrate that CAV1 functions as a tumor suppressor even in the absence of E-cadherin." (PMID 32825247, 2020). "There is evidence that acidic pH conditions favor the delivery of CAV1 in exosomes to less aggressive melanoma cells lacking CAV1." (PMID 32458269, 2020). "B16F10 melanoma cells, expressing CAV1 or not, and AT2R were injected intravenously, after pretreating with either vehicle or CGP42112, and lung tumor mass was determined 21 d later." (PMID 31484460, 2019). "Uveal melanoma cells, however, express a considerably lower, or no amounts of Caveolin 1 compared to melanoma cells of cutaneous origins, such as B16F0 cells." (PMID 30157875, 2018). "Furthermore, the expression of alpha5beta1 integrin is required for lung colonization by B16F10 melanoma cells in C57BL/6 mice and CAV1 has been suggested to participate in the regulation of integrins by a variety of mechanisms." (PMID 27259249, 2016). "Our results indicate that the ECM components fibronectin and laminin (but not vitronectin or collagen) stimulate CAV1 Y14 phosphorylation and that CAV1 promotes melanoma migration on these surfaces, as well as matrigel invasion in a Y14-dependent manner." (PMID 27259249, 2016). "Cav-1 and FASN were found to be co-expressed and related to poor prognosis in patients with pancreatic adenocarcinoma, and a high-fat diet led to upregulation of Cav-1 and FASN and rapid proliferation of melanoma cells." (PMID 27331874, 2016). "Altogether, these results show that melanoma samples lacking PTEN and expressing high level of CAV1 do exist in mouse and human melanomas." (PMID 26307673, 2015). "Lastly, we examined the expression of CAV1 and PTEN in human melanomas." (PMID 26307673, 2015).
melanoma (continued). "Cav-1 and FASN are coordinately regulated and Cav-1 interacts with FASN in melanoma cells." (PMID 26116372, 2015). "Fifty human melanoma samples were stained for PTEN and CAV1 on consecutive slides." (PMID 26307673, 2015). "Finally, in agreement with our in vitro data, histomolecular analysis of human melanoma biopsies revealed the existence of PTEN-negative, CAV1-positive and P16-negative tumour." (PMID 26307673, 2015). "The A375 human melanoma cells have already elevated CAV1 levels compared with non-Mts (data not shown)." (PMID 24500501, 2014). "The expression of this protein in human melanoma development and particularly how the presence of CAV1 affects metastasis after surgery has not been defined." (PMID 24500501, 2014). "B16F10 melanoma cells expressing or not CAV1 were injected subcutaneously and tumours were allowed to grow to a defined size (1500–1800 mm3)." (PMID 24500501, 2014). "Moreover, CAV1 is identified as a negative prognostic marker in melanoma patients undergoing surgery because the presence of the protein at levels comparable to those observed in the human melanoma samples is directly associated in our preclinical surgery models with increased lung metastasis." (PMID 24500501, 2014). "Supporting these data, unpublished data from our group demonstrate increased Cav1 expression in metastatic compared with non-metastatic melanoma cell lines." (PMID 23521716, 2013). "However, plasma exosomes concentration was significantly higher in melanoma patients with respect to healthy individuals (P<0.001 for both CD63+ and Cav1+ exosomes)." (PMID 19381331, 2009). "Regarding the expression of genes associated with cellular processes, melanoma aggressiveness, resistance and cell survival, a significant difference was found in the expression of ABCB5, CAV1 and S100A9 compared with the control (cells not exposed to the extract)." (PMID 36431795, 2022). "Finally, in order to test whether tyrosine-14 phosphorylation affected the role of CAV1 in energy metabolism, we measured lactate production after PTP1B inhibition in mouse melanoma and human breast and colon cancer cell lines." (PMID 35740528, 2022). "Indeed, acidic pH conditions favored exosome-mediated delivery of CAV1 to less aggressive melanoma cells lacking CAV1." (PMID 31362353, 2019). "In summary, the CAV1 residue Y14 is shown here to be essential to promote experimental melanoma metastasis to the lung, while not being required for tumor suppression, indicating that the dual role of CAV1 in cancer is attributable to functionally independent regions of the protein." (PMID 27259249, 2016). "Whether it is important for melanoma cells to maintain CAV1 expression elevated once metastasis has occurred is not clear." (PMID 24500501, 2014). "Caveolin-1 (Cav1) constitutes caveolae majorly in terms of structure and function; once its expression is dysregulated, patients may be prone to not only melanoma but also non-melanoma skin cancer (NMSC) and other hyperproliferative disorders, such as psoriasis." (PMID 37894888, 2023). "Indeed, our group has shown that in the absence of E-cad, CAV1 phosphorylation on tyrosine-14 (Y14) promotes signaling via a novel Rab5-Rac1 axis and, in doing so, enhances migration and invasion in vitro, as well as metastasis in a melanoma model in vivo." (PMID 38069269, 2023). "Importantly, in metastatic MDA-MB-231 cells, CAV1 is highly phosphorylated on Y14 in comparison with non-metastatic cancer cells and in B16F10 melanoma cells CAV1 expression promotes matrix-specific migration, invasion and trans-endothelial migration in a Y14-dependent manner." (PMID 29340103, 2017). "We found that expression of ANXA1, CAV-1, CAV- 2, EphA2, IGFBP2 and PTRF mRNA did not correlate with response to dasatinib in the panel of 8 melanoma cell lines." (PMID 25594008, 2014).